TNF (tumor necrosis factor)
Diseases named in the same sentence as TNF in open-access papers (continued):
Sharing a sentence is not in itself a finding about the gene and the disease.
Yersinia infection (24 papers, 2010 to 2025). "In addition, KEGG pathway analysis revealed that most of the genes were associated with cytokine-cytokine receptor interaction, Yersinia infection, and TNF signaling pathway." (PMID 40435035, 2025). "KEGG Pathways were enriched in Yersinia infection, toll-like receptor signaling pathway, TNF signaling pathway, and other pathways." (PMID 38049739, 2023). "The key KEGGs were mainly related to Cytokine-cytokine receptor interaction (hsa04060), Yersinia infection (hsa05135), IL-17 signaling pathway (hsa04657), and TNF signaling pathway (hsa04668)." (PMID 36285159, 2022). "KEGG analysis showed that the related pathways of QZF in the treatment of SS included the FOXO signaling pathway, Yersinia infection, TNF signaling pathway, and HIF-1 signaling pathway." (PMID 35341135, 2022). "Caspase‐3 can cleave gasdermins E (GSDME) and consequently trigger GSDME‐dependent pyroptosis downstream of LPS/TNF‐α/TAK1 inhibitor co‐stimulation or Yersinia infection or BRAF/MEK inhibitor co‐treatment." (PMID 34590363, 2021). "In the KEGG signaling pathway, DEGs were mainly related to Yersinia infection, Th17 cell differentiation, and the TNF signaling pathway." (PMID 34950188, 2021). "In contrast to GSDMD, GSDME can be cleaved via caspase‐3 in macrophages during Yersinia infection or LPS/TNF‐α/TAK1 inhibitor co‐stimulation." (PMID 33033617, 2020). "Taken together, our work and that of others strongly suggest that the cytolytic functions of CD8+ T-cells in addition to their ability to produce IFN-γ and TNF-alpha are critical to control Yersinia infection." (PMID 28207901, 2017). "To investigate the effect of Ysr170 on host immune response to Yersinia infection, we examined TNF-α, IL-8, and transcription factor EGR1 expression in THP-1 cells infected with wild-type and Ysr170 KD strains." (PMID 28030576, 2016). "In contrast, caspase-8 promotes TLR4-induced NF-κB activation in mouse B cells independent of its protease enzymatic activity, whereas the production of inflammatory cytokines (TNF, IL-6, IL-12) upon Yersinia infection relies on the protease enzymatic activity of caspase-8." (PMID 38789425, 2024). "Interestingly, in addition to the active p30 fragment, it is also observed that GSDMD was cleaved into a p43 and p20 fragment upon Yersinia infection or LPS/TNF‐α/TAK1 inhibitor co‐stimulation." (PMID 33033617, 2020). "In particular, c-KIT is of great interest as a potential biomarker for susceptibility to Yersinia infection, given our preliminary data showing that primary dendritic cells that express higher c-KIT levels produced less TNF-α in response to Y. pestis infection." (PMID 24206648, 2013). "Interestingly, CD8α+ DCs produced less IL-12 and TNF upon Yersinia infection, indicating that Ye specifically targets this cDC subset." (PMID 21124820, 2010). "In murine BMDMs, TNF or TLR stimulation together with pharmacological TAK1 or IKK blockade induces RIPK1- and caspase-8-dependent cell death, similar to Yersinia infection." (PMID 39186805, 2024). "It mainly acts on biological processes such as inflammatory response, chemokine metabolic process, and immune response as well as pathways such as FoxO signaling pathway, Yersinia infection, HIF-1 signaling pathway, and TNF signaling pathway." (PMID 35341135, 2022). "This was consistent with the reported literature: Yersinia infection of epithelium (HeLa) cells can significantly enhance the levels of transcription and secretion of inflammatory cytokines MCP-1, GM-CSF, and TNF-α." (PMID 28507952, 2017). "Furthermore, we demonstrate that activation of RIPK1-dependent pyroptosis in neutrophils during Yersinia infection requires IFN-γ priming, which serves to induce surface TNFR1 expression and amplify soluble TNF secretion." (PMID 38965211, 2024).
Yersinia infection (continued). "Yersinia infection has been shown to induce the assembly of the pro-caspase-8-containing death receptor complex, known as the DISC, independent of TNF or Fas receptor signaling, thereby activating caspase-8." (PMID 23633954, 2013).
Acute hepatitis (23 papers, 2011 to 2025). Acute hepatic injury resulting from inflammation typically accompanied by increased serum alanine transaminase activity. "Inhibition of IDO activity exacerbates liver injury in both α-galactosylceramide- and carbon tetrachloride (CCl4)-induced acute hepatitis models and is associated with the induction of TNF-α." (PMID 24039933, 2013). "CA nanoparticles have also demonstrated the ability to reduce inflammation and apoptosis in acute hepatitis models by decreasing levels of TNF-α, IL-1β, and IL-18, as well as inhibiting NF-κB, NLRP3, and caspase-1, while promoting Bcl-2 levels." (PMID 40869259, 2025). "LY294002 is a pan-PI3K inhibitor, which was proven to inhibit LPS-induced acute hepatitis injury in a murine model and also reduced TNF-α and IL-6 expression." (PMID 36558058, 2022). "As plant lectin concanavalin A (ConA) is another widely used mouse model for introducing immune-mediated acute hepatitis by inducing TNFα, IL-6 and IFNγ, we further detected the role of Bcl-3 in ConA-induced liver injury." (PMID 34853447, 2022). "Specifically, deletion of ADAM17 in myeloid cells completely prevented carbon tetrachloride-induced acute hepatitis, and attenuated endotoxin-induced elevations in circulating TNFα levels." (PMID 35095853, 2021). "In a TNFα-induced acute hepatitis mouse model, the lethality, hypothermia, and influx of leukocytes into the liver are all suppressed by MMP inhibitors, indicating that MMPs play important roles in inflammation associated with acute hepatitis." (PMID 32793588, 2020). "It is interesting to point out that acute treatment of mice with the LRH-1 inhibitor 3d2 did not cause any significant liver damage, yet was able to reduce macrophage-induced and TNF-mediated acute hepatitis." (PMID 32111818, 2020). "To determine how TNFα affected the function of MMPs in acute hepatitis, we assessed the expression and activation of MMPs and the broad MMP inhibitor, TIMPs." (PMID 32793588, 2020). "In CCl4 induced acute hepatitis, the recruited CD11b+ cells produce not only TNF but also FasL, thereby accelerating hepatocyte apoptosis." (PMID 27708340, 2016). "Using the endothelial isoform of nitric oxide synthase knockout (eNOS−/−) mouse model, the functional importance of BVR-eNOS was tested in vivo during acute hepatitis induced by TNF-α and D-galactosamine." (PMID 26719800, 2015). "Based on our observation that serum TNF‐α levels of Ninj1 conventional KO mice were lower than those of WT mice after 5 h of LPS/D‐gal treatment, we supposed lack of Ninj1 in myeloid‐lineage cells, including macrophages, had attenuated the severity of acute hepatitis by reducing TNF‐α production." (PMID 36071453, 2022). "According to a previous knock‐out (KO) study, TNF‐α KO mice and TNFR1 KO mice were completely resistant to LPS/D‐gal‐induced acute hepatitis, whereas TNFR2‐deficient mice were susceptible, which demonstrated this model is wholly dependent on the TNF‐α/TNFR1 death signalling pathway." (PMID 36071453, 2022). "Thus, some works demonstrated the protective role of RIPK1 in hepatocytes during different acute hepatitis involving TNF-α." (PMID 35806372, 2022). "Besides, RIPK1 is known to play a protective role in different type of acute hepatitis involving TNF-α." (PMID 35806372, 2022). "Altogether, these different data probably reflect the coexistence of the protective and harmful properties of TNF-α in acute hepatitis induced by CCl4, a balance which could be influence depending on the experimental conditions." (PMID 35806372, 2022). "Importantly, pharmacological inhibition of LRH-1 was also able to significantly inhibit LPS-induced TNF production in vivo, thus preventing LPS/N-acetyl-d-galactosamine (GalN)-induced, TNF-mediated, acute hepatitis in mice." (PMID 32111818, 2020).
Acute hepatitis (continued). "Our results are consistent with those of recent reports showing that the inhibition of the enzymatic activity of IDO significantly exacerbated liver injury in α-galactosylceramide (α-GalCer)- and CCl4-induced acute hepatitis animal models via the upregulation of IL-6 and TNF-α." (PMID 24039933, 2013). "Similarly, high circulating CD8+ T cells cause the altered and defective monocyte and macrophage differentiation, decreased level of circulating IL-1, and increased secretion of TNF-α, IFN-γ, and IL-2 receptors which causes damage of hepatocytes and subsequently leading to acute hepatitis." (PMID 24232179, 2013). "The transcript level of TNF-α, TRAIL, IL-1β and IL-6 was significantly up-regulated following D-GalN Poly(I:C) induced acute hepatitis (8h) compared to D-GalN or PBS control mice." (PMID 24058536, 2013). "Patients with ALF have higher circulating concentrations of proinflammatory cytokines [e.g., tumor necrosis factor (TNF)-α, interleukin (IL)-1β, and IL-6] than healthy subjects or patients with acute hepatitis." (PMID 21406085, 2011).
chronic fatigue syndrome (23 papers, 2013 to 2024). "Despite the paucity of publications on the associations between TNF-α and prenatal fatigue, this association has been commonly seen in other populations, such as patients with cancer, chronic fatigue syndrome and gastrointestinal disease." (PMID 36193420, 2022). "In the murine model of chronic fatigue syndrome, the combination of AM and AS was found to increase body weight and endurance capacity and to decrease mRNA levels of IL-1β, TNF-α, NF-κB, and p38MAPK." (PMID 31781219, 2019). "It has also been shown to reduce the expression of the pro-inflammatory cytokines tumor necrosis factor-α (TNF-α) and interleukin (IL)-6 in chronic fatigue syndrome (CFS) patients after six-eight weeks of clinical therapy." (PMID 30658449, 2019). "A persistent inflammatory response, characterized by elevated pro-inflammatory cytokines such as TNF, mirrors other conditions like myalgic encephalomyelitis/chronic fatigue syndrome (ME/CFS) and suggests that inflammation continues long after the acute phase of infection." (PMID 39599909, 2024). "We conducted an English-language search of databases, including PubMed, EMBASE, Web of Science, and Google Scholar, by using the terms “Chronic fatigue syndrome” OR “myalgic encephalomyelitis” AND “cytokine” OR “Tumor necrosis factor-α” OR “Interferons” OR “Interleukins” OR “TGF-β”." (PMID 31253154, 2019). "From previous studies it is known that following the TSST, TNF-α production of PBMCs stimulated with LPS may increase in healthy controls or decrease as shown in patients with chronic fatigue syndrome." (PMID 29977237, 2018). "Finally, work on animal models of chronic fatigue syndrome has also underlined the important pathogenic role of TRAF1-related cytokines, such as TNFα." (PMID 23710202, 2013). "TNF-α and IL-6 were found to be increased in patients with OSAS, and TNF-α was found to be increased in narcolepsy, chronic fatigue syndrome and chronic insomniac patients." (PMID 37571368, 2023). "Some studies have suggested that a reduction in tissue inflammation may alleviate chronic fatigue, such as TNF-α, IL-1β, and IFN-γ play a major role in the development of chronic fatigue syndrome." (PMID 34063723, 2021). "Furthermore, TJ-41 may inhibit Tumor Necrosis Factor-α (TNF-α), Interleukin-6 (IL-6), IL-10, Transforming Growth Factor-1 (TGF-1), and Interferon (INF) production, in order to combat chronic fatigue syndrome." (PMID 35736467, 2022). "Other studies reported increased gene expression of IL-10, but not IL-6 or TNF, up to 48 h after a 25-min cycling exercise in FMS comorbid with chronic fatigue syndrome, but no change in patients with FMS only." (PMID 27296860, 2016). "Non-oncologic patients with Chronic Fatigue Syndrome have increased levels of pro-inflammatory cytokines such as IL1 beta, IL 1 receptor antagonist and TNF-alpha, and fatigue is a major side effect of cancer patients receiving interleukins, TNF-alpha and interferon." (PMID 25852820, 2015).
chronic pancreatitis (23 papers, 2010 to 2025). A chronic inflammatory process causing damage and fibrosis of the pancreatic parenchyma. "In particular, TNF inhibitors have been suggested to be a cause of both acute and chronic pancreatitis in a number of cases." (PMID 39712842, 2024). "Inspired by a number of recent case reports, in this study, we investigated the association between TNF inhibitor therapy and acute and chronic pancreatitis." (PMID 39712842, 2024). "Previous analysis of all biochemical parameters in the serum of pigs with cerulein-induced chronic pancreatitis (CP) revealed pancreatic and intestinal inflammation, together with an associated increase in the TNF-α concentration in the mucous membrane of the duodenum and pancreas." (PMID 38396667, 2024). "In this regard, the administration of AR-42 has been reported to suppress the transcriptional expression of pro-inflammatory cytokines, such as IL-1β, TNFα and IL-6, in trinitrobenzene sulfonic acid-induced chronic pancreatitis in mice." (PMID 37728477, 2023). "When administered to mice with chronic pancreatitis, these substances affect the activity of crucial enzymes such as glutathione peroxidase, lipase, and trypsin, as well as tumor necrosis factor-alpha and transforming growth factor beta." (PMID 38255683, 2023). "We found that expression of the fibrosis marker GFAP, α-SMA and the inflammation marker TNF-α, IL-6 increased significantly in chronic pancreatitis when compared to controls." (PMID 32524326, 2020). "In patients with PDAC, serum levels of FGF (P = 0.002), G-CSF (P = 0.037) and TNF-α (P = 0.044) were significantly decreased, compared to patients with chronic pancreatitis." (PMID 29069789, 2017). "The study identified high levels of IL-6 in PDAC cases compared to chronic pancreatitis patients and elevated IL-10 and TNFα in PDAC cases compared to healthy subjects." (PMID 24884871, 2014). "In our experiment, the expression of these inflammatory cytokines or mediators in the pancreas of chronic pancreatitis mice were quantified with q-PCR assay and showed that sulindac treatment significantly decreased the expression of TNF-α and MCP-1 mRNA in the pancreas." (PMID 22920325, 2012). "The mRNA levels of TNF-α and MCP-1 in the pancreatic tissue was significantly increased in caerulein induced chronic pancreatitis mice compared to the control mice." (PMID 22920325, 2012). "Indeed, KC;iASPPΔ8/Δ8 pancreas-infiltrating CD4+ and CD8+ T cells secreted substantially less (p = 0.037) TNF-α and IFN-γ following chronic pancreatitis." (PMID 36746936, 2023). "TNF-α and C-reactive protein indices were higher in patients with chronic pancreatitis and T2DM than those with isolated chronic pancreatitis, characterizing the persistence of chronic systemic inflammation in case of the combined clinical course of these diseases." (PMID 33456608, 2020). "The role of cytokines/chemokines in the pancreatic homeostasis may demonstrate among others studies on p38 mitogen-activated protein kinase which upregulates various cytokines and chemokines including IL-6, TNF-α, and MCP-1 and at the same time suppresses chronic pancreatitis." (PMID 31624954, 2019).
dysplasia (23 papers, 2013 to 2025). A usually neoplastic transformation of the cell, associated with altered architectural tissue patterns. "TNF-α antagonists not only inhibit CAC induction in mice by limiting TNF-induced infiltration of neutrophils and macrophages but also reduce the risk of both dysplasia and CAC when combined with other anti-inflammatory medications in the clinic." (PMID 34675913, 2021). "Finally, there was also distinct trend toward increased intestinal neoplasia (dysplasia or cancer) and toward an increased use of aggressive treatments (anti-TNFα or anti-α4β7 integrin) in SHIP1-deficient CD." (PMID 29872435, 2018). "Persistent exposure to inflammatory cytokines—such as IL-6, IL-8, and TNF-α—can induce urothelial hyperplasia, metaplasia, and eventually dysplasia, thereby contributing to recurrence." (PMID 41375065, 2025). "Serum IL-17A, IL-23, and TNF-α increased at the inflammation and dysplasia stage, and the IL-23 dramatically elevated in the 6th week particularly." (PMID 35615089, 2022). "An increase in TNF-α expression occurs in esophageal epithelial cells during the metaplasia-dysplasia-carcinoma progression." (PMID 29449669, 2018). "Confirming these data, TNF-α expression has been shown to increase along the metaplasia-dysplasia-carcinoma sequence, leading to an increase in the proto-oncogene MYC via a β-catenin mediated pathway." (PMID 28042960, 2017). "Pro-inflammatory cytokines were expressed by colorectal M1 macrophages during inflammatory hyperplasia (IL-1β, IL-6) and dysplasia (IL-12, TNF-α), thus indicating that MI macrophages have a positive role during the process of carcinoma." (PMID 25434400, 2015). "In the present study, the overexpression of NF-κB and epithelial TNF-α was positively correlated to the intensity of the inflammatory infiltrate in dysplasia." (PMID 23833665, 2013). "Furthermore, erythroid and megakaryocytic dysplasia are associated with increased production of IFN-γ and TNF in the bone marrow of dogs infected with L. infantum." (PMID 34442696, 2021). "TNF-α in both epithelial and stromal cells and NF-κB exhibited a direct, statistically significant correlation with the intensity of the inflammatory infiltrate in the cases of dysplasia." (PMID 23833665, 2013). "In Barrett’s esophagus, increased expression levels of IFN-γ and TNF-α have been reported and TNF-α seems to increase along the metaplasia–dysplasia–carcinoma sequence." (PMID 32100077, 2020). "Immunoreactivity using IHC analysis has shown significantly higher expression of TNF-α in OSCCs and OPMDs with and without dysplasia compared to normal controls." (PMID 36980727, 2023). "Salivary TNF-α was significantly higher in patients with OSCC compared to patients with OPMDs without dysplasia or OLP with a trend of an increase in dysplasia, which was not significantly different from OSCC." (PMID 36980727, 2023). "The results of the present study did not reveal significant differences in salivary concentration of IL-1α, IL-6, IL-8, and TNF-α between patients with OPMDs without dysplasia and healthy individuals." (PMID 32245251, 2020). "There was also significant increase in salivary concentrations of IL-6, IL-8 and TNF-α in patients with OSCC as compared to patients with OPMDs without dysplasia." (PMID 32245251, 2020). "There is an increase in the mean values of salivary TNF – α levels in different grades of OED from mild dysplasia to severe dysplasia, but the values are not statistically significant." (PMID 31350970, 2019). "However, our inverse associations with dysplasia are consistent with a previous study that found that IL‐2, IL‐5, IL‐8, IL‐10, IL‐13 and TNF‐alpha tend to be downregulated in low‐grade/moderate dysplasia of the pancreas compared to serous cystadenoma without dysplasia." (PMID 39482824, 2025).